PLIN2 (perilipin 2)
Diseases named in the same sentence as PLIN2 in open-access papers (continued):
Sharing a sentence is not in itself a finding about the gene and the disease.
steatosis (continued). "ATGL-deficient mice at 12–13 weeks of age demonstrated microvesicular steatosis of the liver shortly before cardiac death, with increased expression of perilipin 2 and slight downregulation of perilipin 5, as measured by immunohistochemistry." (PMID 36611868, 2022). "H&E and Plin2 staining of liver sections at p14 further confirmed the accumulation of small lipid droplets (microvesicular steatosis) in the hepatocytes of Hmgcs2-KO mice." (PMID 35421611, 2022). "We demonstrated previously that compared with a control liquid diet, an alcohol liquid diet promotes steatosis, PLIN2 upregulation, and ceramide accumulation in a temporal pattern." (PMID 32398264, 2020). "In HF/HSD-fed AEG-1fl/fl mice, PLIN2 staining unraveled significantly high levels of microvesicular and macrovesicular steatosis and 100% large hepatocellular ballooning (HB) with strong intensity in male mice and 35% small to 25% medium HB with moderate intensity in female mice." (PMID 41448428, 2025). "In mouse hearts, Plin2 is upregulated during fasting-induced steatosis." (PMID 39588271, 2024). "Notably, Plin2 is a predominant member of the Plin protein family in both rat and human livers, and its expression correlates strongly with the severity of steatosis." (PMID 38673735, 2024). "We hypothesized that fluorescence labeling of lipid droplets by tagging the endogenous PLIN2 locus might enable the development of an imaging-based steatosis drug-screening system." (PMID 36823355, 2023). "However, in the later stages of NAFL, the size of LDs increases considerably, and PLIN2 is replaced by PLIN1, a hallmark of LD maturation and macrovesicular steatosis." (PMID 37958873, 2023). "Importantly, H&E and Plin2 stainings of liver sections showed greater hepatosteatosis, specifically microvesicular steatosis, in Hmgcs2-HET mice compared to WT mice." (PMID 35421611, 2022). "H&E and Plin2 staining of p21 liver sections revealed that, in contrast to the severe microvesicular steatosis seen in Hmgcs2-KO mice at suckling, the livers of Hmgcs2-KO early-wean mice exhibited a significant reduction in lipid accumulation, making their phenotype comparable to those of WT mice." (PMID 35421611, 2022). "In particular, a reduction in Plin2 immunostaining, which emphasizes small lipid droplets, depicted a shift from diffuse microvesicular steatosis to focal macrovesicular steatosis at liver tissue periphery in early-wean Hmgcs2-KO mice, associated with better clinical outcomes of fatty liver." (PMID 35421611, 2022). "Notably, this effect of thiamine reversed the strong dietary effect of the HC diet in increasing perilipin 2 transcripts, thus reflecting the observed pattern of steatosis in LC, HC and THC animals." (PMID 33608323, 2021). "Concomitant with the increase in PPARγ2 expression, overexpressing JMJD2B stimulated the expression of hepatosteatosis genes including fatty acid uptake-associated genes CD36, FABP4 and lipid droplet-associated genes PLIN2, CIDEC in HepG2 cells, which are known PPARγ2 steatosis target genes." (PMID 30214048, 2018). "Our results support earlier studies showing that the PLIN2-peroxisome proliferator-activated receptor pathway, a marker for induction of steatosis, is upregulated in hepatocyte-like cells induced with OA, and that downregulation of PLIN2 is associated with ER stress resolution." (PMID 30254132, 2018). "Thus, PLIN2-reporter organoids act as real-time lipid reporter systems, providing the possibility of higher throughput and semiautomated analysis of drug effects on steatosis." (PMID 36823355, 2023). "Moreover, the expression of Plin2, which encodes the major lipid droplet-binding protein Adipocyte Differentiation Related Protein in hepatocytes, was increased in the liver of DIO mK293Q mice, affirming the hepatic steatosis phenotype." (PMID 37213714, 2022). "Thus, pharmacologic modulation of the CB1-perilipin 2 axis might represent a novel therapeutic approach for the treatment of steatosis." (PMID 31570772, 2020).
steatosis (continued). "Experimental data demonstrates that PLIN2 overexpression leads to the excessive hepatic TG accumulation characteristic of NAFLD, and PLIN2-knockout mice were resistant to diet-induced steatosis and inflammation." (PMID 41515601, 2025). "Expression of hepatic genes related to lipid metabolism (Cpt1a, Atgl, Mgl, Dgat2, Srebp, Plin2) and OS (catalase, Edem) were modulated by FB23, although hepatic steatosis remained unchanged." (PMID 39984825, 2025). "It has been shown that loss of PLIN2 in hepatocytes partially protected Western diet-fed mice from steatosis and largely from NASH, whereas overexpression of PLIN2 elevates both TG and LDs." (PMID 35513069, 2022). "OMT significantly decreased the expressions of L-FABP, Plin2, FASN and SCD1 and increased Sirt1 expression and AMPKα phosphorylation in the liver of rats with steatosis." (PMID 32210812, 2020). "Concomitant with reduced PPARγ2 expression, the expression of its steatosis target genes including CD36, FABP4 and PLIN2, CIDEC was also reduced." (PMID 30214048, 2018). "Plin2 is upregulated in experimental models of ALD, is a reliable marker of steatosis in alcohol fed rats, and coats large lipid droplets in mice fed a high fat, ethanol diet." (PMID 24831094, 2014). "It was proven that specific knockout of PLIN2 would reduce mice liver triglycerides, enhance ATGL expression, lipophagy, and fatty acid oxidation by mitochondria, and mitigate LD accumulation, thereby preventing steatosis." (PMID 41559682, 2026). "In contrast, our results from the STZ group revealed a decrease in Plin2 expression, correlating with the absence of steatosis in livers from STZ rats." (PMID 38673735, 2024). "Such limitations are especially relevant when analyzing Plin2 function in the liver, given that Plin5 binds and regulates the activity of ATGL, steatosis is exacerbated in Pnpla2 (ATGL)−/− mice, and as shown in this study, Plin5 is overexpressed in Plin2−/− livers." (PMID 37844775, 2023). "Counterstaining of the reporters with a lipid droplet dye confirmed faithful tagging of lipid droplets, and tagging of PLIN2 did not alter steatosis phenotypes." (PMID 36823355, 2023). "In liver biopsies with moderate to strong steatosis, perilipin 2 was only detected in hepatocytes, but not in non-parenchymal cells." (PMID 36555099, 2022). "In liver biopsies without steatosis, perilipin 1 was negative, whereas perilipin 2 localized to the rim of LDs in non-parenchymal cells, most presumably HSCs, and only to a few LDs in the hepatocytes." (PMID 36555099, 2022). "Therefore, the inhibition of lipophagy along with the continuous production of small LDs engulfed by PLIN2, PLIN3, and PLIN5 could be a proposed mechanism for NAFLD progression from simple steatosis to NASH." (PMID 37958873, 2023). "Interestingly, in the livers of hepatocyte-specific perilipin 2 knockout mice treated with an HFD and CDAA diet, leading to steatosis and steatohepatitis, upregulation of perilipin 5 was observed concomitant to a decrease in inflammation, cell death and fibrosis (parallel manuscript in preparation)." (PMID 36611868, 2022). "In turn, impaired CMA failed to degrade PLIN2 and disrupted cellular lipid homeostasis, thus leading to NSAID-induced steatosis and hepatotoxicity." (PMID 35265214, 2022).
Insulin resistance (32 papers, 2013 to 2026). Increased resistance towards insulin, that is, diminished effectiveness of insulin in reducing blood glucose levels. "In peripheral tissues, Plin2 upregulation promotes lipid retention in settings such as fatty liver, atherosclerosis, and insulin resistance, while Plin2 deficiency reduces lipid burden and inflammation." (PMID 41294836, 2025). "Elevated levels of Plin2 are often associated with various metabolic disorders, including insulin resistance and type 2 diabetes in human and animals." (PMID 38668364, 2024). "It has been suggested that perilipin 2 plays an essential role in lipid storage in muscle by enhancing fatty acid uptake and triglyceride storage in myofibers, thereby blunting lipotoxicity-associated insulin resistance." (PMID 34064680, 2021). "For instance, the rs35568725 (p.S251P) variant in Perilipin-2 (PLIN2) gene, which regulates the stability and the remodeling of LDs and VLDL lipidation, predisposes to severe insulin resistance (IR) and atherosclerosis." (PMID 38846491, 2024). "Often associating with TAG accumulation and protection against lipotoxicity derived-insulin resistance, PLIN2 is known to abound on the surface of LDs." (PMID 36901715, 2023). "Adrp/Plin2-ASO improves diet-induced insulin resistance and inhibits the expression of lipid synthesis-related genes, thereby decreasing liver fat accumulation." (PMID 36569303, 2022). "In other work, mice treated with anti-sense Plin2 oligonucleotides were protected against diet-induced insulin resistance when fed high fat diets." (PMID 24040030, 2013). "Moreover, similar protein expression patterns have been observed in skeletal muscle, indicating a potential role of PLIN2 in regulating glucose uptake and insulin resistance." (PMID 39064723, 2024). "Experimental research suggests that PLIN2 is involved in the pathophysiology of insulin resistance." (PMID 34572396, 2021). "Our study reveals that hepatic-specific loss of PLIN2 reduces hepatic TAG but does not reduce adiposity or improve insulin resistance in mice fed a WTD for 12 weeks." (PMID 33923083, 2021). "In light of these, the elevated expression of Plin2 in the hypothalamus might contribute to insulin resistance of GK rats." (PMID 31579613, 2019). "Indirect evidence that Plin2 is also involved with managing glucose levels comes from several studies including work with the Zucker diabetic rat model which showed increased levels of Plin2 in skeletal muscle correlated with insulin resistance when fed a high fat diet." (PMID 24040030, 2013). "On the basis of these previous results, it could be expected that in old age, where insulin resistance takes place, the expression of Plin2 may be decreased." (PMID 23977392, 2013). "Conversely, downregulating the fatty acid oxidation genes Pnpla2 and Plin2 may promote the formation of intracellular lipid droplets, while downregulating the Irs2 gene may induce insulin resistance and inhibit autophagy in liver cells, ultimately triggering NAFLD." (PMID 37047411, 2023). "Moreover, in skeletal muscle PLIN2 is correlated with insulin resistance." (PMID 33735111, 2021). "Interestingly, PLIN2 deficiency had a beneficial effect on insulin sensitivity, suggesting that loss of PLIN2 was able to protect against ALD-associated hepatic insulin resistance, an effect that may be secondary to impaired hepatic lipid accumulation in these mice." (PMID 35864895, 2022). "Relatively lower expression of PLIN2 can promote the reduction of hepatic fibrosis and enhance insulin sensitivity, while simultaneously suppressing PLIN2 and PLIN3 can lead to insulin resistance." (PMID 29678171, 2018). "Moreover, we did not observe correlations between PLIN2 serum levels and glycated hemoglobin (HbA1c, r = −0.090, p = 0.355) or homeostasis model assessment-insulin resistance (HOMA-IR, r = −0.173, p = 0.077)." (PMID 34572396, 2021).
Insulin resistance (continued). "However, while these reports supported a link between Plin2 and insulin resistance leading to diabetes, no direct experimental evidence was given to explain these observations at the cellular level." (PMID 24040030, 2013). "Our current results show that the increases in hepatic ceramides are prevented in the absence of Plin2 suggesting that Plin2 may mediate both cellular ceramide metabolism and insulin resistance in ALD, thus making Plin2 a potential target for therapy and/or prevention of ALD." (PMID 24831094, 2014).
atherosclerosis (27 papers, 2012 to 2025). A disease characterized by the build-up of fatty material and calcium deposition in the arterial wall resulting in partial or complete occlusion of the arterial lumen. "In ApoE-deficient mice (ApoE−/−), Plin2 promoted foam cell formation and its inactivation led to less formation of LDs and protection from atherosclerosis." (PMID 39859272, 2025). "PLIN2’s degradation pathway markedly lowers the inflammation associated with a high-fat diet, preventing atherosclerosis formation." (PMID 39030618, 2024). "Further studies indicate that apolipoprotein E-deficient (APOE (-/-)) mice exhibit PLIN2 gene inactivation, reducing LD numbers in foam cells within atherosclerotic lesions, potentially protecting against atherosclerosis." (PMID 39030618, 2024). "Among them, Perilipin-2 (PLIN2) rs35568725 (Ser251Pro) variant has been associated with IR and atherosclerosis, in two population studies." (PMID 34680476, 2021). "For the first time, we show that the Pro251 variant in PLIN2 is associated with decreased subclinical atherosclerosis as well as smaller necrotic core sizes and decreased macrophage infiltration in advanced atherosclerotic plaques." (PMID 31251843, 2019). "In the present work, we sought to delineate the role of PLIN2 in human atherosclerosis using the Ser251Pro variant in PLIN2 as a genetic tool." (PMID 31251843, 2019). "More recently, PLIN2 expression was also associated with atherosclerosis in patients with carotid stenosis." (PMID 29196750, 2017). "Previously we showed that targeting perilipin-2 (PLIN2), a major lipid droplet (LD)-associated protein in macrophages, prevents foam cell formation and protects against atherosclerosis." (PMID 22427949, 2012). "Deficiency of PLIN2 in the murine model of atherosclerosis protects from atherogenesis." (PMID 38362263, 2023). "PLIN2 is associated with LD formation and foam cell differentiation in atherosclerosis." (PMID 36237431, 2022). "Since PLIN2 is central for macrophage foam cell formation and we have previously shown that a PLIN2 variant influences plasma lipid profiles 7, we hypothesized that the Pro251 variant in PLIN2 would affect atherosclerosis development." (PMID 31251843, 2019). "The association between PLIN2 and plasma aβ may be due to atherosclerosis; perilipin-2 aids foam cell formation and is overexpressed in atherosclerotic plaques which produce aβ." (PMID 28704393, 2017). "Previously we showed that PLIN2 deficiency protects apoE-deficient mice against atherosclerosis." (PMID 22427949, 2012). "PLIN2+ MPs are found in atherosclerosis plaques, cholesterol polyps of the gall bladder, and fat necrosis." (PMID 37781924, 2023). "PLIN2 has been reported to promote LD formation and form cell differentiation in atherosclerosis, and its subcellular localization is associated with LD." (PMID 36237431, 2022). "There has been evidence of PLIN2 involvement in the development of age-related vascular disease, such as atherosclerosis." (PMID 34572396, 2021). "Recently, we have characterized a common protein variant in PLIN2 (Pro251), which is associated with a less atherogenic plasma lipid profile 7, suggesting that this genetic variant may modulate macrophage foam cell formation and affect proneness to atherosclerosis." (PMID 31251843, 2019). "We show that PLIN2 modulates subclinical atherosclerosis, macrophage foam cell formation and cholesterol efflux by initiating a feed‐forward loop where LXR and autophagy reciprocally activate each other." (PMID 31251843, 2019). "In summary, we demonstrate that PLIN2 modulates subclinical atherosclerosis by reducing lipid retention in the vascular wall and macrophage infiltration." (PMID 31251843, 2019). "We provide evidence for the potential involvement of one of these lncRNAs, lnc-KDM5D-4, in atherosclerosis and CAD, possibly through the lipid metabolism-associated gene PLIN2 in hepatocytes." (PMID 29196750, 2017).
atherosclerosis (continued). "In vivo, PLIN2 mRNA is upregulated in carotid endarterectomy specimens and in atherosclerosis-studded arteries of apoE−/− mice compared to control healthy arteries." (PMID 22427949, 2012). "Importantly in relation to atherosclerosis, genes related to lipid metabolism, which featured in resident macrophages, were downregulated (Plin2, Trem2, Lipa, Msr1, and Abcg1) by CLEC4A2 deletion." (PMID 35017526, 2022). "Additionally, there has been evidence connecting PLIN2 to the development of age-related vascular disease, such as atherosclerosis." (PMID 34572396, 2021). "Since we have previously shown that the Pro251 variant of PLIN2 is associated with a more profitable plasma lipid profile and PLIN2 initiates murine atherosclerosis, we investigated whether PLIN2 modulates development of human atherosclerosis." (PMID 31251843, 2019). "Previously we showed that targeting PLIN2 reduces foam cell formation and atherosclerosis." (PMID 22427949, 2012). "The data support the safety of targeting PLIN2 to prevent foam cell formation and atherosclerosis." (PMID 22427949, 2012). "Moreover, transcriptome profiling has shown that PLIN2 was significantly increased in macrophage foam cells, which are a hallmark of atherosclerosis, in comparison to macrophages without foam cells." (PMID 39859272, 2025). "On the other hand, our study shows that the Pep_A6 vaccine can regulate the expression of liver genes such as Fitm2, Gk, Plin2, Acsl1, Fatp1, and Acot4, thereby lowering serum LDL-C levels and hepatic lipid accumulation while improving atherosclerosis." (PMID 39329770, 2024). "Our data propose that PLIN2 modulates a feed‐forward loop where LXR and autophagy reciprocally activate each other, which ultimately has repercussions on foam cell formation, cholesterol efflux and development of subclinical atherosclerosis progression." (PMID 31251843, 2019). "Here we have studied the response of BMM isolated from mice that do or do not express PLIN2, in terms of apoptosis, ER stress and inflammation, to multiple culture conditions that mimic the lipid environment in different stages of atherosclerosis development." (PMID 22427949, 2012).